EP300 (EP300 lysine acetyltransferase)
Diseases named in the same sentence as EP300 in open-access papers (continued):
Sharing a sentence is not in itself a finding about the gene and the disease.
ovarian carcinoma (18 papers, 2015 to 2025). A malignant neoplasm originating from the surface ovarian epithelium. "RNA sequencing results revealed that disturbance of transcriptome was observed in shNTPCR ovarian cancer cells, and several miRNAs and TFs were predicted to be hub genes correlated with ovarian cancer, including hsa-miR-124-3p, hsa-miR-146a-5p, hsa-miR-30a-5p, EP300, GATA2, and STAT3." (PMID 34539736, 2021).
Intellectual disability (16 papers, 2014 to 2025). "As compared to patients with the CREBBP gene variant, patients carrying the EP300 gene variant have a relatively milder clinical phenotype, particularly milder skeletal abnormalities of the thumbs and toes and less severe intellectual disability." (PMID 37085840, 2023). "These genes include one that has been previously linked to SCZ, Autism Spectrum Disorder and Intellectual Disability (SHANK3) as well as two novel genes that were identified through a protein:protein interaction study (EP300 and MAPK14)." (PMID 26039597, 2015). "Participant 176 is a 37-month-old male with ROHs noted on chromosomes 3, 17, and 22 within regions where several genes (i.e., POU1F1, RAI1, and EP300) associated with intellectual disability are found." (PMID 25400949, 2014). "Additionally, Chinese patients with EP300 variants frequently present with mild intellectual disability, alongside higher rates of intrauterine growth restriction (IUGR), microcephaly, and prenatal complications." (PMID 41347065, 2025). "The co-expression network analysis identified EP300 as a candidate gene for autism, intellectual disability, seizure, hypotonia, and language impairment." (PMID 38002941, 2023). "Rubinstein-Taybi syndrome type 2 (RSTS2; OMIM #613684) is a rare autosomal dominant disorder caused by loss-of-function variants in the EP300 gene (OMIM #602700), characterized by intellectual disability, distinctive craniofacial features, and skeletal anomalies." (PMID 41347065, 2025). "EP300 regulates transcription activators and may be involved in autism, intellectual disability, and seizures." (PMID 38002941, 2023). "However, as the HAT domain is highly conserved between CBP and p300, it is possible that missense mutations involving the HAT domains of both genes (CBP, EP300) lead to typical RTS dysmorphisms and intellectual disability." (PMID 31924266, 2020).
triple-negative breast carcinoma (14 papers, 2020 to 2025). An invasive breast carcinoma which is negative for expression of estrogen receptor (ER), progesterone receptor (PR), and human epidermal growth factor receptor 2 (HER2). "The EP300-G211S mutation was exclusively identified in the triple-negative breast cancer patients, and its presence was significantly associated with overall other pathological somatic mutational patterns." (PMID 35242279, 2022). "In TNBC specific EP300 mutations have been described and EP300 was included in the triple negative breast cancer team project biomarker panel." (PMID 33167919, 2020). "EP300 has been associated with the metastatic capacity of triple-negative breast cancer." (PMID 38731867, 2024). "Consistent with previous results, CREBBP/EP300 HAT inhibition shows activity in a subset of triple negative breast cancer (TNBC) cell lines, but we also noticed potent growth inhibition in ER+ cell lines." (PMID 35353838, 2022). "The other CoREST complex member, LSD1, was reported to repress ABCC1 and ABCC10 gene expression upon inhibition of EP300 in the triple-negative breast cancer cell line MDA-MB-231." (PMID 35205642, 2022). "EP300 knockdown abolished the cancer stem cell phenotype by reducing sphere formation capacity in vitro as well as tumor formation in a xenograft mouse model in triple-negative breast cancer." (PMID 35242497, 2022).
myocardial infarction (13 papers, 2015 to 2025). Gross necrosis of the myocardium, as a result of interruption of the blood supply to the area, as in coronary thrombosis. "Overexpression of EP300 could also promote LV remodeling after myocardial infarction." (PMID 36910531, 2023).
Sepsis (13 papers, 2014 to 2026). Sepsis is defined as life-threatening organ dysfunction caused by a dysregulated host response to infection. "In acute lung injury caused by sepsis, phosphorylated STAT3 recruits EP300 to form a complex that promotes the acetylation of histones H3 and H4 at the NLRP3 promoter, leading to cellular pyroptosis." (PMID 41513612, 2026). "Our analysis revealed that both JUN and EP300 play crucial roles in the two sepsis induction models." (PMID 37510271, 2023). "This network uncovered regulatory interactions among genes like MPO, CXCR2, ITGAM, SPI1, SPI1 and EP300, suggesting these TFs may participate in sepsis-related immune responses and inflammatory regulation by modulating the transcriptional activity of core genes." (PMID 41259376, 2025). "In sepsis-induced acute lung injury, phosphorylated STAT3 recruits EP300, promoting acetylation of the histone region of the NLRP3 gene and thereby facilitating pyroptosis." (PMID 41513612, 2026).
endometrial carcinoma (12 papers, 2010 to 2025). A malignant tumor arising from the epithelium that lines the cavity of the uterine body. "EP300 is a significant driver gene often mutated in endometrial cancer." (PMID 34643467, 2021). "EP300, which co-regulates target proteins along with SIRT1, has recently been reported to increase the acetylation of the RNA splicing gene DDX5 promoter, promoting the progression of endometrial cancer." (PMID 41170449, 2025).
pulmonary fibrosis (12 papers, 2018 to 2026). Chronic progressive interstitial lung disorder characterized by the replacement of the lung tissue by connective tissue, leading to progressive dyspnea, respiratory failure, or right heart failure. "Increased activity and expression of EP300 was observed to be associated with different diseases, including pulmonary fibrosis and acute respiratory distress syndrome." (PMID 37373058, 2023). "It was also observed that genetic deficiency and pharmacological inhibition of EP300 could abrogate pulmonary fibrosis both in vitro and in vivo." (PMID 37373058, 2023). "Overall, inhibition of the CBP/EP300 histone acetyltransferase activity by plumbagin appears to be a potential therapeutic approach for managing pulmonary fibrosis." (PMID 37569677, 2023). "Moreover, the upregulation of Discoidin domain receptor 1 (DDR1), a transmembrane collagen receptor, and EP300 was observed in samples from healthy or idiopathic pulmonary fibrosis (IPF) patients by single-cell RNA sequencing." (PMID 37569677, 2023).
acute lymphoblastic leukemia (11 papers, 2015 to 2025). Leukemia with an acute onset, characterized by the presence of lymphoblasts in the bone marrow and the peripheral blood. "EP300 promotes acute lymphoblastic leukemia by regulating TCF3 HLF (American Association for Cancer Research, 2020)." (PMID 34149798, 2021). "A study in Hispanic Americans has demonstrated that rs20551 gene variant in EP300 plays an important role in childhood acute lymphoblastic leukemia." (PMID 28725161, 2017). "Critically, recurrent chromosomal translocations involving the ZNF384 gene, which result in fusion proteins with partners such as EWSR1, TAF15, and EP300, are frequently observed in the pathogenesis of acute lymphoblastic leukemia (ALL)." (PMID 41429980, 2025). "EP300 dysfunction presents another compelling therapeutic target in acute lymphoblastic leukemia." (PMID 41181124, 2025).
esophageal squamous cell carcinoma (11 papers, 2014 to 2024). Esophageal squamous cell carcinoma (ESCC) is a type of esophageal carcinoma (EC) that can affect any part of the esophagus, but is usually located in the upper or middle third. "E1A Binding Protein P300 (EP300) is one of the mutations of genes involved in histone modifications in esophageal squamous cell carcinoma (ESCC)." (PMID 31632486, 2019). "In esophageal squamous cell carcinoma (ESCC), cAMP-response element binding protein binding protein (CBP) and EP300 up-regulates the expression of LINC00460 through binding to the promoter of LINC00460 and regulating its chromatin architecture." (PMID 34094983, 2021).
follicular lymphoma (11 papers, 2017 to 2025). Follicular lymphoma is a form of non-Hodgkin lymphoma characterized by a proliferation of B cells whose nodular structure of follicular architecture is preserved. "Approximately 39% of DLBCL and 41% of follicular lymphoma patients contain inactivated mutations in the CREBBP or EP300 genes and are commonly seen in GBC-DLBCL." (PMID 37884941, 2023). "In addition, each contingent showed its own pathogenic variants, such as BCL2, KMT2D, EP300 in the follicular lymphoma contingent, and XPO1, TNFAIP3, and CREBBP in the cHL contingent." (PMID 36428786, 2022). "Mutations in the histone acetylation domain of EP300 are present in 14% of the samples, similar to what is seen in DLBCL and follicular lymphoma." (PMID 29340061, 2017).
lung adenocarcinoma (11 papers, 2016 to 2025). A carcinoma that arises from the lung and is characterized by the presence of malignant glandular epithelial cells. "Similar to our research, miR-342 might promote lymph node metastasis in lung adenocarcinoma by targeting EP300." (PMID 32925795, 2020). "CRISPR/Cas9‐mediated deletion (1,555–1,727 bp) of a part of the super‐enhancer region of MYC, which is bound by the transcriptional co‐activator EP300, reduced the expression of MYC by ~30% in human H2009 lung adenocarcinoma cells." (PMID 28255028, 2017).
tauopathies (11 papers, 2012 to 2025). "Inhibitors have been explored as potential therapeutic agents; for example, a past study has shown that specific EP300 inhibitors can mitigate tauopathy and associated cognitive deficits in cellular models of Alzheimer’s disease." (PMID 38002524, 2023). "Dysregulated EP300 activity has been linked to neurodegenerative diseases, particularly Alzheimer’s disease, where its hyperacetylation of tau, a microtubule-associated protein, has been observed, suggesting a potential mechanism for tauopathy, the aggregation of aberrant tau proteins in the brain." (PMID 38002524, 2023). "MiR-132 provides neuroprotection for tauopathies via regulating the tau modifiers acetyltransferase EP300, kinase GSK3β, RNA-binding protein Rbfox1 and proteases Calpain2 and Caspases 3/7." (PMID 30881384, 2019).
breast tumor (10 papers, 2006 to 2024). "EP300 downregulation resulted in a more malignant phenotype of breast tumors with the acquisition of drug resistance, although the mechanistic explanation was not presented in this study." (PMID 36674511, 2023). "CREBBP, EP300, ESR1, GATA3, and MYC are well-known genetic biomarkers and mutate frequently in breast tumors." (PMID 34235216, 2021). "Breast cell lines showed downregulation of HDAC1, HDAC2, HDAC5, EZH2, EP300, and PCAF compared to breast tumours." (PMID 16638127, 2006).
esophageal cancer (10 papers, 2013 to 2025). A primary or metastatic malignant neoplasm involving the esophagus. "With a FDR adjusted P‐value of 0.002, EP300‐related ceRNAs showed the tendency of expression down‐regulated according to one EP300 gene knockdown profile of oesophageal cancer cell line (GSE74742)." (PMID 30421585, 2019). "Collectively, the variation of EP300 may be involved in the tumorigenesis and development of esophageal cancer." (PMID 31632486, 2019). "Our results demonstrated that EP300 protein showed strong nuclear staining in esophageal carcinoma tissues whereas nearly negative in matched normal tissues." (PMID 31632486, 2019).
Hepatic steatosis (10 papers, 2014 to 2024). Steatosis is a term used to denote lipid accumulation within hepatocytes. "EP300 is a general TF that regulates cell growth and division and has been reported as a key participant in hepatic steatosis." (PMID 25399255, 2014).
Insulin resistance (10 papers, 2011 to 2025). Increased resistance towards insulin, that is, diminished effectiveness of insulin in reducing blood glucose levels. "As MASH is a multifactorial disease with triggers such as dyslipidemia, insulin resistance, inflammation, and oxidative stress, the roles of EP300 in these aspects of the disease were also explored." (PMID 39399467, 2024).
pancreatic ductal adenocarcinoma (10 papers, 2010 to 2024). An infiltrating adenocarcinoma that arises from the epithelial cells of the pancreas. "EP300 has been shown to be downregulated by microRNA in highly metastatic pancreatic ductal adenocarcinomas, demonstrating the capacity for MeSHOP comparison to identify candidate disease genes." (PMID 23021552, 2012). "Here, we report that E1A binding protein P300 (EP300) acetyltransferase promotes ferroptosis in human pancreatic ductal adenocarcinoma (PDAC) cells via the acetylation of heat shock protein family A (Hsp70) member 5 (HSPA5), also known as GRP78 or BIP) on the site of K353." (PMID 37696842, 2023).
Alzheimer disease (9 papers, 2012 to 2024). A progressive, neurodegenerative disease characterized by loss of function and death of nerve cells in several areas of the brain leading to loss of cognitive function such as memory and language. "However, in our iPSC-neurons, EP300 or CBP knockdown reduced total H3K27ac abundance, which correlated with widespread downregulation of gene transcription in both APPDup and NDC neurons, including important genes in Alzheimer’s disease pathways." (PMID 38167174, 2024).
Cognitive impairment (9 papers, 2017 to 2025). Abnormal cognition is characterized by deficits in thinking, reasoning, or remembering. "This suggests a pathological link between defects in chromatin regulation (e.g., mutations in CBP/EP300 encoding p300) and aberrant RNA processing as a potential central mechanism underlying cognitive impairment." (PMID 40507967, 2025). "Mutations in EP300 have been reported in patients with Rubinstein–Taybi syndrome, which is characterized by cognitive impairment." (PMID 38396891, 2024). "The expression of the EP300 gene is associated with cognitive deficits in schizophrenia." (PMID 40364201, 2025). "Fragile X syndrome protein (FMRP) is associated with EP300, and the loss of FMRP increases EP300 and HDAC1 levels in adult NSCs, resulting in age-related NSC depletion and cognitive impairment in mouse models." (PMID 38396891, 2024).
fibrosis (9 papers, 2019 to 2025). the formation of excess fibrous connective tissue in an organ or tissue in a reparative or reactive process. "Collectively, these data indicate CREBBP/EP300 is a highly associated pathway in localized human fibrosis that controls key aspects of myofibroblast phenotype and function, including ACTA2 and COL1A1 gene expression and cell contractility." (PMID 32759223, 2020).
liver fibrosis (9 papers, 2018 to 2025). "Altogether, the siRNA results and results obtained with two small-molecule inhibitors tested on HSCs and LX-2 cells confirm the causal role of EP300 in liver fibrosis, which is in agreement with the results from our weighted, directional data-driven disease network." (PMID 39399467, 2024). "A recent report on EP300, which was published toward the end of our study, further supports this observation, as do the in vivo observations uncovered during our target efficacy analysis, showing that EP300 knockout or knockdown can reduce liver fibrosis and its underlying processes." (PMID 39399467, 2024). "Recently, Ep300 histone acetyl-transferase was reported to be a therapeutic target for treatment of liver fibrosis." (PMID 41415834, 2025). "In our experimental validation of in silico target selection, we confirmed EP300 as a gene relevant to liver fibrosis." (PMID 39399467, 2024). "For instance, some reports suggest that the phosphorylation of EP300 by AKT signaling triggers its translocation to the nucleus during liver fibrosis." (PMID 37569677, 2023). "The roles of EP300 in liver fibrosis were further supported by in vitro and in vivo studies." (PMID 39399467, 2024). "The experimental results thus substantiate the governing role of EP300 in liver fibrosis." (PMID 39399467, 2024). "Three targets, including EP300, were confirmed for their roles in liver fibrosis." (PMID 39399467, 2024). "For example, liver fibrosis was reduced in CCl4-treated EP300 knockout mice." (PMID 39399467, 2024). "One of these targets is histone acetyltransferase (HAT) EP300, which is used to exemplify the construction, analysis, and validation of the MASH-induced liver fibrosis network for target discovery." (PMID 39399467, 2024). "Abrogation of EP300 activity was as efficient to attenuate fibrosis in vitro and in vivo as the cholangiocyte-selective EP300 KO, in a ACTA2-AS1 dependent manner, which indicates the reversible cooperation between EP300 and lncRNAs during liver fibrosis." (PMID 37569677, 2023).
myelodysplastic syndrome (9 papers, 2019 to 2024). A clonal hematopoietic disorder characterized by dysplasia and ineffective hematopoiesis in one or more of the hematopoietic cell lines. "In a mouse model of human myelodysplastic syndrome, deletion of EP300 significantly accelerates leukemogenesis." (PMID 35836809, 2022).
schizophrenia (9 papers, 2017 to 2025). A major psychotic disorder characterized by abnormalities in the perception or expression of reality. "Specifically, the index SNV rs20551 at 22q13.2 locus (PLACO P = 5.07 × 10−11 for IBS-schizophrenia) was a significant eQTL for EP300 (OMIM 602700) encoding p300 protein, which plays an important role in cell proliferation and differentiation." (PMID 36753304, 2023). "Previous studies have found that common and rare variants of EP300 are associated with schizophrenia risk." (PMID 34483940, 2021). "Exploration of DNA methylation at placentally expressed genes of the PRS for schizophrenia revealed methylation at cg06793497 (EP300 gene) to be associated with CPR (β = 0.021, t = 4.385; p = 0.00008, FDR-adjusted p = 0.11)." (PMID 31072398, 2019). "Notably, this syndrome is associated with a higher risk to develop schizophrenia, among other psychiatric conditions; interestingly, EP300 gene is located on chromosome 22 at position 22q13.2." (PMID 31072398, 2019). "In Subject 2, we identified a 3′ UTR SNP in EP300 (c.*13_*15del; AF: 0.245; CADD score: 15.8), a common variant previously associated with reduced schizophrenia risk." (PMID 41463395, 2025). "Further, we identified three loci shared between neuroticism and schizophrenia, which were annotated to FLJ10661 (rs2945232; non-coding transcript exon variant), TNKS (rs2048656; intergenic) and EP300 (rs11090039; intronic)." (PMID 28533504, 2017). "Additionally, methylomic exploration of schizophrenia PRS genes known to be expressed in placenta revealed the association between CPR and EP300 gene CpG-specific methylation, at the cg06793497 probe, in our monochorionic twin sample." (PMID 31072398, 2019). "Integration of the schizophrenia PRS with obstetric and placental information, allowed the identification of E1A binding protein p300 (EP300) gene CpG-specific methylation as a putative marker of exposure to prenatal stress." (PMID 31072398, 2019).